PSMD6 (proteasome 26S subunit, non-ATPase 6)
Description:
Component of the 26S proteasome, a multiprotein complex involved in the ATP-dependent degradation of ubiquitinated proteins. This complex plays a key role in the maintenance of protein homeostasis by removing misfolded or damaged proteins, which could impair cellular functions, and by removing proteins whose functions are no longer required. Therefore, the proteasome participates in numerous cellular processes, including cell cycle progression, apoptosis, or DNA damage repair.
Synonyms: KIAA0107; S10; p44S10; Rpn7; SGA-113M; p42A
Tractability: Small molecule: an approved drug acts on it; a structure with a bound ligand is known; a high-quality ligand is known. Antibody: its Gene Ontology location is reachable by antibodies, with high confidence. PROTAC: ubiquitination databases record sites on it; its protein half-life has been measured.
Target class: Enzyme
Gene: Protein-coding gene on chromosome 3 (64,010,549 to 64,024,010, reverse strand). Ensembl gene ENSG00000163636.
Pathways (Reactome):
Immune System: AMPK-induced ERAD and lysosome mediated degradation of PD-L1(CD274); Activation of NF-kappaB in B cells; Antigen processing: Ubiquitination & Proteasome degradation; CLEC7A (Dectin-1) signaling; Cross-presentation of soluble exogenous antigens (endosomes); Dectin-1 mediated noncanonical NF-kB signaling; Downstream TCR signaling; ER-Phagosome pathway; FCERI mediated NF-kB activation; GSK3B-mediated proteasomal degradation of PD-L1(CD274); Interleukin-1 signaling; NIK-->noncanonical NF-kB signaling; Neutrophil degranulation; SPOP-mediated proteasomal degradation of PD-L1(CD274); TNFR2 non-canonical NF-kB pathway
Cell Cycle: APC/C:Cdc20 mediated degradation of Securin; APC/C:Cdh1 mediated degradation of Cdc20 and other APC/C:Cdh1 targeted proteins in late mitosis/early G1; Autodegradation of Cdh1 by Cdh1:APC/C; Autodegradation of the E3 ubiquitin ligase COP1; Cdc20:Phospho-APC/C mediated degradation of Cyclin A; FBXL7 down-regulates AURKA during mitotic entry and in early mitosis; G2/M Checkpoints; SCF(Skp2)-mediated degradation of p27/p21; SCF-beta-TrCP mediated degradation of Emi1; Separation of Sister Chromatids; The role of GTSE1 in G2/M progression after G2 checkpoint; Ubiquitin-Mediated Degradation of Phosphorylated Cdc25A; Ubiquitin-dependent degradation of Cyclin D
Signal Transduction: Asymmetric localization of PCP proteins; Degradation of AXIN; Degradation of DVL; Degradation of GLI1 by the proteasome; Degradation of GLI2 by the proteasome; Degradation of beta-catenin by the destruction complex; GLI3 is processed to GLI3R by the proteasome; Hedgehog 'on' state; Hedgehog ligand biogenesis; MAPK6/MAPK4 signaling; Negative regulation of NOTCH4 signaling; Regulation of PTEN stability and activity
and 28 more pathways
Gene Ontology:
Molecular function: protein binding
Biological process: cellular response to type I interferon; proteasomal protein catabolic process; proteasome-mediated ubiquitin-dependent protein catabolic process; regulation of proteasomal protein catabolic process; response to oxidative stress
Cellular component: proteasome complex; cytosol; extracellular region; ficolin-1-rich granule lumen; nucleoplasm; proteasome accessory complex; proteasome regulatory particle; secretory granule lumen; synaptic vesicle; protein-containing complex
Genetic constraint (gnomAD): Loss-of-function variants: 7 observed, 40.24 expected, observed/expected ratio (o/e) 0.17, 90% interval 0.098 to 0.33. The upper end of that interval is the gene's LOEUF score, 0.33, which puts it in group 1 of 6, group 1 being the genes least tolerant of losing a copy. Missense variants: 417 observed, 490.72 expected, observed/expected ratio (o/e) 0.85, 90% interval 0.78 to 0.92. Synonymous variants: 183 observed, 174 expected, observed/expected ratio (o/e) 1.05, 90% interval 0.93 to 1.19.
Homologues: Orthologues: chimpanzee PSMD6 (100% identical), macaque PSMD6 (99% identical), pig PSMD6 (99% identical), rabbit PSMD6 (99% identical), guinea pig PSMD6 (98% identical), mouse Psmd6 (98% identical), rat Psmd6 (98% identical), tropical clawed frog psmd6 (93% identical), zebrafish psmd6 (92% identical), dog PSMD6 (92% identical), Drosophila melanogaster Rpn7 (70% identical), Caenorhabditis elegans rpn-7 (48% identical). Paralogues in human: GPS1 (23% identical).
Diseases named in the same sentence as PSMD6 in open-access papers:
PSMD6 is named in the same sentence as 22 diseases in open-access papers, as found by Europe PMC text mining. Sharing a sentence is not in itself a finding about the gene and the disease. The quoted sentences say what the papers report.
diabetes (3 papers, 2015 to 2022). "The PSMD6 variant rs831571 has been identified as a susceptibility locus for type 2 diabetes mellitus (T2DM)." (PMID 26024304, 2015). "The PSMD6 gene encodes a member of the S10 family of protease subunits, and PSMD6 gene variation may be related to the therapeutic effect of diabetes." (PMID 36698419, 2022).
type 2 diabetes (3 papers, 2013 to 2021). "In conclusion, we observed that the PSMD6 variant rs831571 might be associated with the therapeutic efficacy of rosiglitazone and repaglinide in Chinese patients with type 2 diabetes." (PMID 26024304, 2015). "Several type 2 diabetes mellitus (T2DM) susceptibility loci have been identified in or near GLIS3, PEPD, FITM2-R3HDML-HNF4A, KCNK16, MAEA, GCC1-PAX4, PSMD6, and ZFAND." (PMID 34822452, 2021).
breast carcinoma (2 papers, 2008 to 2020). "Genes such as NCOA3, PPM1D, PSMD6 and BCAS2 were detected with high expression and copy numbers in MCF-7 cells, and these genes have been associated with breast cancer progression." (PMID 18350142, 2008).
pancreatic ductal adenocarcinoma (2 papers, 2023). An infiltrating adenocarcinoma that arises from the epithelial cells of the pancreas. "In pancreatic ductal adenocarcinoma patients, high levels of PSMD6, PSMD9, PSMD11, and PSMD14 are associated with a lower rate of survival." (PMID 36934426, 2023). "In another study, the expression of PSMD6, PSMD9, PSMD11, and PSMD14 was significantly associated with a decreased chance of survival in patients with pancreatic ductal adenocarcinoma." (PMID 37349676, 2023).
asthma (1 paper, 2025). "The results identified MEblack as a cluster containing 741 asthma-related core genes, including POMP, GUSBL2, RBM39, PSMA6, RFX1, TCEB1, PSMD6, and others." (PMID 41403444, 2025).
esophageal squamous cell carcinoma (1 paper, 2022). Esophageal squamous cell carcinoma (ESCC) is a type of esophageal carcinoma (EC) that can affect any part of the esophagus, but is usually located in the upper or middle third. "Other reports demonstrated a role for PSMD6 in lung adenocarcinoma and esophageal squamous cell carcinoma." (PMID 36498916, 2022).
pancreatic tumor (1 paper, 2025). "Systematic evaluation of PSMD1-14 expression revealed significant upregulation (p<0.05) of PSMD1, PSMD2, PSMD3, PSMD4, PSMD7-PSMD14 transcripts in pancreatic tumor tissues compared with adjacent normal controls, with the notable exception of PSMD6 which demonstrated reduced mRNA expression." (PMID 40182048, 2025).
Peri-Implantitis (1 paper, 2019). An inflammatory process with loss of supporting bone in the tissues surrounding functioning DENTAL IMPLANTS. "Three leader genes (PSMD10, SOS1, WASF3), eight cross-talk genes (PSMD10, PSMD6, EIF2S1, GSTP1, DNAJC3, SEC61A1, MAPT, and NME1), and one signaling pathway (IL-17 signaling) emerged as peri-implantitis and T2DM linkage mechanisms." (PMID 31275749, 2019).
psoriasis (1 paper, 2023). An autoimmune condition characterized by red, well-delineated plaques with silvery scales that are usually on the extensor surfaces and scalp. "Two members of the first cluster, PSMD1 and PSMD6, have previously been reported as key drivers of psoriasis in a human multi-omics study." (PMID 37521042, 2023).
sarcopenia (1 paper, 2026). Progressive decline in muscle mass due to aging which results in decreased functional capacity of muscles. "By using ML algorithms and expression analysis techniques, this study further validated several URGs including CBLB, PSMD6, RNF115, SMAD3, UCHL3 and ZBTB16 as potential markers associated with sarcopenia." (PMID 41560007, 2026).
tumor (5 papers, 2014 to 2025). "Eight proteins were upregulated in the hippocampus in response to sustained tumour growth, including Psmd6, Rps28, calretinin (Calb2) and Pdcd6." (PMID 40172096, 2025). "The effect of PSMC4 and PSMD6 expression in tumor progression is still unclear." (PMID 35497331, 2022).
cancer (3 papers, 2014 to 2025). A tumor composed of atypical neoplastic, often pleomorphic cells that invade other tissues. "The deficiency of PSMD6 delays DNA repair and leads to a decline in cell survival, which may offer new therapeutic approaches for cancer." (PMID 36003381, 2022). "Clusters 3 and 5 showed elevated expression of genes associated with cancer development and progression, such as CEBPB, PLIN2, PRDX1, PSMD6, and TXNRD1." (PMID 39805002, 2025). "Similar uPAR-dependent DNA damage-induced PSMD6 nuclear import was also observed in H2O2 treated cells as assessed by immunocytochemistry and cell fractionation and in MDA-MB 231 cancer cells." (PMID 24987841, 2014).
infection (1 paper, 2023). The state of being infected such as from the introduction of a foreign agent such as serum, vaccine, antigenic substance or organism. "After 24 h of infection, the expression levels of UBE2C and PSMD6 the expression levels returned to unstimulated baseline levels, while SUMO1, SUMO2 and PSMC1 showed slightly higher expression levels than uninfected control cells." (PMID 37165081, 2023).
PSMD6 also shares sentences with these, for which no sentence is quoted: autism (2 papers); multiple myeloma (2); cyst (1); Epstein-Barr virus infection (1); glioma (1); hypoplastic left heart syndrome (1); lung adenocarcinoma (1); lung carcinoma (1); nematode infection (1).